USP9X (ubiquitin specific peptidase 9 X-linked)
Diseases named in the same sentence as USP9X in open-access papers (continued):
Sharing a sentence is not in itself a finding about the gene and the disease.
Sepsis (2 papers, 2024 to 2025). Sepsis is defined as life-threatening organ dysfunction caused by a dysregulated host response to infection. "The deubiquitinating enzymes breast cancer susceptibility protein 1 (BRCA1)-associated protein 1 (BAP1) and USP9x are also involved in sepsis-induced AKI through the NF-κB signaling pathway." (PMID 40225869, 2025). "In sepsis, the level of USP9X is upregulated in CD8+ T cells, and this upregulation contributes to the development of sepsis by causing dysfunction in CD8+ T cells." (PMID 38322269, 2024). "In a sepsis-induced AKI model, USP9x inhibits the ubiquitinated degradation of toll-like receptor 4 (TLR4), which is involved in inflammatory responses and apoptosis by activating the NF-κB signaling pathway through interaction with lipopolysaccharide (LPS)." (PMID 40225869, 2025).
tauopathies (2 papers, 2024 to 2025). "Our findings highlight Raptor and USP9X as promising molecular targets for therapeutic intervention in tauopathies." (PMID 39449082, 2024). "Our findings highlight Raptor and USP9X as potential therapeutic targets for tauopathy, offering promising avenues for novel treatment strategies." (PMID 39449082, 2024). "Given the established links between USP9X, autophagy, and tau phosphorylation, investigating the potential role of USP9X in regulating tau protein levels through Raptor deubiquitination in the context of tauopathy is of paramount importance." (PMID 39449082, 2024). "This decision allowed us to isolate the specific role of USP9X in tauopathy without the confounding factor of sex hormones." (PMID 39449082, 2024).
Turner syndrome (2 papers, 2016 to 2020). Turner syndrome is a chromosomal disorder associated with the complete or partial absence of an X chromosome. "USP9X, an X-linked gene, is differentially expressed across sexes in the adult mouse brain, and is hypothesized to play a role in differential neural development in women with XO Turner syndrome." (PMID 27467526, 2016). "Furthermore, a haploinsufficiency-like mechanism of USP9X-female NDD is not supported by e.g. phenotypes observed in Turner Syndrome with XO sex chromosome karyotype, which generally lack neurological manifestations." (PMID 33298948, 2020).
α-synucleinopathies (2 papers, 2013 to 2019). "Like AF-6, the soluble forms of the synphilin-1 isoform, synphilin-1A and USP9X are decreased in α-synucleinopathies." (PMID 23393160, 2013). "It has been suggested that drugs that modulate the activity of USP9X, together with enhancers of autophagy or proteasomal activity, may help decrease the levels of α-synuclein and provide a novel therapeutic strategy to treat α-synucleinopathies." (PMID 31130875, 2019).
adenovirus infection (1 paper, 2022). "We suggest a model for adenovirus infection in which USP9x acts indirectly to negatively regulate pIIIa-RANBP2 interactions." (PMID 35709296, 2022).
Autoimmunity (1 paper, 2015). The occurrence of an immune reaction against the organism's own cells or tissues. "Thus, increased degradation of Itch in the absence of USP9x could provide an alternative explanation for the increased autoimmunity in Usp9x-deficient mice." (PMID 26732666, 2015).
B-cell acute lymphoblastic leukemia (1 paper, 2016). A neoplasm of lymphoblasts committed to the B-cell lineage, typically composed of small to medium-sized blast cells. "For instance, in the setting of B-cell acute lymphoblastic leukemia (B-ALL) interference with Usp9X caused bax-dependent apoptosis and suppression of the pro-survival mTORC1 signaling pathway." (PMID 26872380, 2016).
brain cancer (1 paper, 2013). A primary or metastatic malignant neoplasm affecting the brain. "Taken together, our studies demonstrate that knockdown of USP9X drastically alters the growth characteristics of brain cancer cells." (PMID 23667531, 2013). "To begin to understand the roles of SOX2-associated proteins in brain cancer, we focused on two SOX2-associated proteins, Musashi 2 (MSI2) and Ubiquitin Specific Protease 9x (USP9X)." (PMID 23667531, 2013). "We also examined whether USP9X is required for the survival of brain cancer cells." (PMID 23667531, 2013).
carcinoma in situ (1 paper, 2013). "We also noticed that the USP9X expression increased gradually in the transformation from low grade intraepithelial neoplasia to high grade intraepithelial neoplasia as carcinoma in situ in which the full-thickness epithelium showed intensive immunostaining for USP9X." (PMID 24152793, 2013).
cataract (1 paper, 2023). Partial or complete opacity of the crystalline lens of one or both eyes that decreases visual acuity and eventually results in blindness. "Anterior segment anomalies are not currently associated with USP9X, yet our cases demonstrate ARA, congenital glaucoma, corneal neovascularization, and cataracts." (PMID 37895297, 2023).
chordoma (1 paper, 2024). Chordomas are rare malignant tumors arising from embryonic remnants of the notochord in axial skeleton. "Our genomic data confirmed previous findings that PIK3CA and chromatin remodeling genes were among the most frequently mutated genes in chordoma, while the potential driver role of LYST and USP9X were less certain." (PMID 39135136, 2024).
ciliopathy (1 paper, 2022). A genetic disorder of the cellular cilia or the cilia anchoring structures, the basal bodies, or of ciliary function. "UPS components have also been shown to interact with ciliopathy proteins, such as USP9X with lebercilin, and the UPS was an enriched biological module that we identified in a whole genome siRNA screen of ciliogenesis." (PMID 35170427, 2022). "Part of this regulation appears to be mediated by a functional association of the ciliary apparatus with the UPS, and UPS components have been shown to interact with ciliopathy proteins (e.g. USP9X and lebercilin)." (PMID 35170427, 2022).
Cognitive impairment (1 paper, 2023). Abnormal cognition is characterized by deficits in thinking, reasoning, or remembering. "Dominant loss-of-function and missense variants in USP9X are well-recognized as a cause of syndromic cognitive impairment." (PMID 37895297, 2023). "Features unique to USP9X include abnormal pigment distribution along lines of Blaschko, choanal atresia, polydactyly, agenesis of the corpus callosum, and a higher rate of cognitive impairment." (PMID 37895297, 2023).
diabetic nephropathy (1 paper, 2023). "USP9X has been shown to inhibit the pathogenesis of diabetic nephropathy through multiple mechanisms." (PMID 36834633, 2023). "Overexpression of Usp9x in these cells attenuated glucose-induced epithelial-to-mesenchymal transition (EMT) in a DUB activity–dependent manner, which is a pathology associated with diabetic nephropathy." (PMID 36834633, 2023). "USP9X in renal epithelial cells, and USP22 in renal epithelial cells and mesangial cells have beneficial effects on diabetic nephropathy." (PMID 36834633, 2023).
Dyscalculia (1 paper, 2022). A specific learning disability involving mathematics and arithmetic. "In addition, we found a likely pathogenic missense variant in USP9X (p.Y1268C) which was inherited from her mother who had dyscalculia and dyspraxia during her school career." (PMID 35227307, 2022).
Epileptic encephalopathy (1 paper, 2015). A condition in which epileptiform abnormalities are believed to contribute to the progressive disturbance in cerebral function. "USP9X mutations were identified by resequencing a cohort of patients with epileptic encephalopathy, one patient harbored a de novo missense mutation and another a novel coding mutation." (PMID 25763846, 2015). "One male patient, T17133, presented with epileptic encephalopathy and was found to carry a de novo USP9X mutation (c.3034T>C, p.Ser1012Pro) at a highly conserved residue (GERP 5.62) that was predicted to be possibly damaging by PolyPhen (0.898)." (PMID 25763846, 2015).
goblet cell adenocarcinomas (1 paper, 2023). "Mutations in the USP9X gene are associated with Turner syndrome, syndromic and X-linked female-restricted intellectual developmental disorder, and X-linked intellectual developmental disorder, being also reported in a single case of appendiceal goblet cell adenocarcinoma." (PMID 37509254, 2023).
head and neck cancer (1 paper, 2021). A primary or metastatic malignant neoplasm affecting the head and neck. "Further ongoing experiments are necessary to fully understand centrosome biology (>100 centrosome proteins exist) in multiple cell lines lacking USP9X pre- and post-irradiation, particularly those originating from head and neck cancers, which is our research and clinical focus." (PMID 34277417, 2021).
hereditary spherocytosis type 2 (1 paper, 2024). "Reverse phenotyping by pediatric hematology confirmed the diagnosis of hereditary spherocytosis type 2 related to the SPTB variant, while the pathogenic variant in USP9X explained the ID/DD phenotype and most of the dysmorphic features." (PMID 38560291, 2024).
Hyperglycemia (1 paper, 2023). An increased concentration of glucose in the blood. "USP22 in pancreatic β-cells, USP2 in adipose tissue macrophages, USP9X, 20, and 33 in myocytes, USP4, 7, 10, and 18 in hepatocytes, and USP2 in hypothalamus improve hyperglycemia, whereas USP19 in adipocytes, USP21 in myocytes, and USP2, 14, and 20 in hepatocytes promote hyperglycemia." (PMID 36834633, 2023).
Infertility (1 paper, 2022). "USP9X-null spermatogenic cells underwent apoptotic cell death at the early spermatocyte stage and then caused subsequent aberrant spermiogenesis, which resulted in complete infertility of USP9X conditional knockout male mice." (PMID 36277066, 2022).
intestinal cancer (1 paper, 2018). "Although the E3 ligase Itch was shown to mediate the antitumor effects of USP9X in the pancreas, our data demonstrate that USP9X can prevent intestinal cancer by directly regulating the stability of FBW7 protein." (PMID 29346117, 2018). "Importantly, the regulation of FBW7 by USP9X has implications in human intestinal cancer." (PMID 29346117, 2018).
intraepithelial neoplasia (1 paper, 2013). A precancerous neoplastic process that affects the squamous, glandular, or transitional cell epithelium without evidence of invasion. "Nevertheless, there was a significance in USP9X expression between low grade intraepithelial neoplasia and high grade intraepithelial neoplasia (P = 0.012)." (PMID 24152793, 2013). "Furthermore, level of high USP9X expression increased gradually in the transformation from normal epithelium (4.0%), low grade intraepithelial neoplasia (10.5%), high grade intraepithelial neoplasia (28.6%), to invasive ESCC (40.2%)." (PMID 24152793, 2013). "We observed that the level of high USP9X expression increased gradually in the transformation from normal epithelium (4.0%), to low grade intraepithelial neoplasia (10.5%), then to high grade intraepithelial neoplasia (28.6%), and finally to invasive ESCC (40.2%)." (PMID 24152793, 2013). "The expression of USP9X was found to be significantly different between the normal mucosa and ESCC (P < 0.001), and between low grade intraepithelial neoplasia and high grade intraepithelial neoplasia (p = 0.012)." (PMID 24152793, 2013). "However, both between normal mucosa and low grade intraepithelial neoplasia (P = 0.369), and between high grade intraepithelial neoplasia and ESCC (P = 0.115), no significance was detected in the high expression of USP9X." (PMID 24152793, 2013).
ischemic heart disease (1 paper, 2026). "Collectively, these findings establish the USP9X-TRAFD1 axis and its CMA-mediated degradation as critical checkpoints in post-MI inflammation, highlighting USP9X stabilization as a therapeutic strategy for ischemic heart disease." (PMID 41604579, 2026).
laryngeal carcinoma (1 paper, 2023). Carcinoma that arises from the laryngeal epithelium. "The decreased expression of USP9X subsequently reduced Mcl-1 expression and increased Bax expression, which may be the cause of apoptosis in laryngeal cancer cells." (PMID 37057289, 2023). "The purpose of this study was to comprehensively analyze the expression of USP9X, its effect on the cell cycle function, and its role in the formation and development of laryngeal cancer." (PMID 37057289, 2023). "Abnormal expression of USP9X in laryngeal cancer was closely related to gender, clinical stages, degree of differentiation and lymphatic metastasis (p < 0.05)." (PMID 37057289, 2023). "To verify the effect of USP9X on the biological behavior of laryngeal cancer cells, we performed proliferation, migration, invasion, and apoptosis assays using the constructed USP9X-siRNA-FaDu cells." (PMID 37057289, 2023). "The USP9X mRNA level in laryngeal cancer tissues was approximately 1.65 times that in the adjacent tissues (p < 0.001)." (PMID 37057289, 2023). "The expression rule of USP9X in laryngeal cancer tissues can provide a valuable reference for the diagnosis, treatment, and prognostic evaluation of laryngeal cancer." (PMID 37057289, 2023). "QRT-PCR and WB analysis showed that there was a significant increase in USP9X mRNA transcription and protein levels in laryngeal cancer tissues, suggesting that USP9X was highly expressed." (PMID 37057289, 2023). "The level of USP9X in laryngeal cancer was higher than that in adjacent tissues, which is consistent with the abnormal expression of USP9X in malignant tumors of other organs." (PMID 37057289, 2023). "The expression of USP9X protein in most laryngeal cancer tissues (31/36) was higher than that in the adjacent tissues." (PMID 37057289, 2023). "QRT-PCR analysis showed that the expression of USP9X mRNA in laryngeal cancer tissues was higher than that in the adjacent tissues." (PMID 37057289, 2023). "The expression of USP9X was significantly correlated with degree of laryngeal cancer differentiation and lymphatic metastasis." (PMID 37057289, 2023). "The role of deubiquitinating enzyme USP9X in the occurrence and development of laryngeal cancer must be further studied." (PMID 37057289, 2023). "This study attempted to analyze the clinical significance and relationship between USP9X expression and laryngeal cancer progression." (PMID 37057289, 2023). "The relationship between USP9X expression in 36 fresh tissues and different clinical parameters of enrolled patients with laryngeal cancer also has been analyzed." (PMID 37057289, 2023). "We demonstrated that there was a clear increase in the level of USP9X in clinical laryngeal cancer tissues compared with adjacent tissues." (PMID 37057289, 2023). "Our findings for the first time suggest the expression level and trend of USP9X in laryngeal cancer tissue and USP9X can potentially promote the occurrence and development of laryngeal cancer, providing a theoretical basis for further study of laryngeal cancer cell biology." (PMID 37057289, 2023). "In this study, we found that USP9X was upregulated in laryngeal cancer tissues." (PMID 37057289, 2023). "However, this differed significantly with the degree of differentiation (p < 0.05), indicating that abnormal expression of USP9X in laryngeal cancer was related to the parameter." (PMID 37057289, 2023). "WB analysis showed that USP9X protein was expressed in paraneoplastic and laryngeal cancer tissues." (PMID 37057289, 2023). "The expression of USP9X in 36 cases of laryngeal cancer tissues were examined by qRT-PCR and WB." (PMID 37057289, 2023). "The expression of USP9X in 86 cases of laryngeal cancer tissues were examined by IHC." (PMID 37057289, 2023). "Therefore, the function and regulatory mechanism of USP9X in laryngeal cancer must be further studied." (PMID 37057289, 2023).
laryngeal carcinoma (continued). "Our findings for the first time suggest the expression level and trend of USP9X in laryngeal cancer tissue and USP9X may plays an important role in promoting the occurrence and progression of laryngeal cancer." (PMID 37057289, 2023). "Therefore, USP9X is an important factor that promotes containment, and its role in the tumors depends on the background and species and its impact on laryngeal cancer must be further studied at the cellular level." (PMID 37057289, 2023). "Therefore, we speculated that USP9X was positively correlated with the malignant progression of laryngeal cancer." (PMID 37057289, 2023). "USP9X may be a potential intervention target for the treatment of laryngeal cancer." (PMID 37057289, 2023). "USP9X may be a potential target for intervention in treatment of laryngeal cancer." (PMID 37057289, 2023). "Combined with the analysis of IHC results and clinical data, it was concluded that abnormal increased expression of USP9X in laryngeal cancer tissues was not correlated with sex, age, stage, or lymph node metastases, but was correlated with the degree of differentiation." (PMID 37057289, 2023). "However, the involvement of USP9X in the formation and regulation of cancer has not been clearly studied, and the specific function of USP9X in laryngeal cancer needs to be confirmed in further studies." (PMID 37057289, 2023).
laryngeal tumor (1 paper, 2023). "This study was divided into two parts: 1) Study on the expression of USP9X in laryngeal tumor tissues by IHC, qRT-PCR, and WB assay; 2) Study on the changes of biological behavior of FaDu cells by using USP9X siRNA." (PMID 37057289, 2023).
malignant glioma (1 paper, 2015). A grade III or grade IV glioma arising from the central nervous system. "Usp9X has not been targeted for clinical therapy in malignant glioma." (PMID 26008975, 2015).
mantle cell lymphoma (1 paper, 2024). Mantle cell lymphoma is a rare form of malignant non-Hodgkin lymphoma affecting B lymphocytes in the lymph nodes in a region called the ``mantle zone''. "Furthermore, USP9X upregulation plays a key role in the formation of mantle cell lymphoma (MCL) via different pathways, including enhanced cell proliferation and cell cycle, inhibition of cell death, and induction of angiogenesis." (PMID 39664521, 2024).
memory impairment (1 paper, 2024). "Reducing EV secretion, interfering with miR-142-5p expression or overexpressing ACTN4, ELAVL4 and USP9X ameliorated memory impairment and rescued CNP-associated dendritic spine changes." (PMID 38632655, 2024). "miR-142-5p was identified as the key molecule responsible for pathological SC-EVs-mediated memory impairment, and α-actinin-4 (ACTN4), ELAV-like protein 4 (ELAVL4, also known as HuD) and ubiquitin-specific peptidase 9 X-linked (USP9X) were identified as novel target molecules of miR-142-5p." (PMID 38632655, 2024).
myeloid neoplasm (1 paper, 2020). Proliferation of myeloid cells originating from a primitive stem cell. "In this study, we examine the efficacy of the USP9X inhibitors WP1130 and G9 on cells expressing wild-type JAK2 or JAK2-V617F, including the ruxolitinib-persistent cells, comparably, to explore the therapeutic potentials of USP9X inhibition against JAK2-V617F-driven myeloid neoplasms." (PMID 32050632, 2020).
myeloproliferative neoplasm (1 paper, 2020). A clonal hematopoietic stem cell disorder, characterized by proliferation in the bone marrow of one or more of the myeloid (i.e., granulocytic, erythroid, megakaryocytic, and mast cell) lineages. "Thus, the present study proposes USP9X inhibitors along with BH3 mimetics as promising agents for novel therapeutic strategies against JAK2-V617F-positive myeloproliferative neoplasms, particularly under the ruxolitinib persistence condition." (PMID 32050632, 2020). "Thus, USP9X represents a promising target along with anti-apoptotic Bcl-2 family members for novel therapeutic strategies against JAK2-V617F-positive myeloproliferative neoplasms, particularly under the ruxolitinib persistence conditions." (PMID 32050632, 2020).